SYNE1 (spectrin repeat containing nuclear envelope protein 1)
Diseases named in the same sentence as SYNE1 in open-access papers (continued):
Sharing a sentence is not in itself a finding about the gene and the disease.
breast carcinoma (16 papers, 2011 to 2025). "Dysregulation, dysfunction, or mutation in SYNE1/Nesprin-1 plays an important role in oral cancer, glioblastoma, breast cancer, ovarian cancer and HCC, possibly through the regulation of cell proliferation and apoptosis." (PMID 34944636, 2021). "The most extreme cohort-independent changes in lifetime survival were observed in Syne1 (HR = 0.17) and Pdcd4 (HR = 4.68), and the former profile has been found in lung, ovarian, colon, and breast cancers; while, the second has been associated with glioma." (PMID 21649900, 2011). "Gene enrichment analysis in terms of Jensen DISEASES revealed that genes with germline variants (PLXNA2, FAT2, and SYNE1) enriched in the Maltese breed are also enriched in several cancers, such as endometrial cancer (p < 0.01), pancreatic cancer (p < 0.05), and breast cancer (p < 0.05)." (PMID 31842489, 2019). "Our findings were further validated using qRT-PCR, western blotting and immunohistochemistry which show decreased expression of NLGN3, MAML2, ANK2, and SYNE1 in breast cancer cell lines as MCF7 and MDA-MB-231 as compared to control cell line MCF10A." (PMID 38977697, 2024). "The unpaired student’s t-test showed the decrease in protein expression of ANK2, SYNE1 and NLGN3 was significant in the cancer cell lines MDA-MB-231 (p-value < 0.05) when compared with control MCF10A and decrease in protein expression of SYNE1 was significant in MCF7 breast cancer cell line." (PMID 38977697, 2024). "FAT3, MUC16, and SYNE1 have also been mentioned as common mutant genes in breast cancer in previous studies, but there is no specific report on whether they affect the development and prognosis of breast cancer." (PMID 33968045, 2021).
autosomal recessive cerebellar ataxia type 1 (14 papers, 2014 to 2024). "Pathogenic mutations in SYNE1 are associated with spinocerebellar ataxia, autosomal recessive 8 (SCAR8) (OMIM: 610743)." (PMID 39214971, 2024). "Mutations in SYNE1 have been identified in patients suffering from spinocerebellar ataxia and autosomal recessive 8 (SCAR8), as well as Emery–Dreifuss muscular dystrophy." (PMID 36799927, 2023). "Mutations in SYNE1, coding for nesprin-1, have been reported to cause neurodegenerative diseases such as “Autosomal Recessive Cerebellar Ataxia type 1” (ARCA1), also called “Autosomal recessive ataxia, Beauce type”." (PMID 30245638, 2018). "Mutations in SYNE1 are associated with human autosomal recessive cerebellar ataxia [e.g. autosomal recessive cerebellar ataxia type 1 (ARCA1) or autosomal recessive spinocerebellar ataxia-8 (SCAR8)]." (PMID 26035387, 2015). "Mutations in the SYNE1 gene have been found to cause autosomal recessive cerebellar ataxia type 1 (ARCA1) and SYNE1 has recently been implicated as a susceptibility gene for BPD in a large collaborative GWAS study." (PMID 25393678, 2014). "The most prevalent disease resulting from SYNE1 mutations is autosomal recessive cerebellar ataxia type 8 (SCAR8), also known as autosomal recessive cerebellar ataxia type 1 or recessive ataxia of Beauce." (PMID 39519078, 2024). "Autosomal recessive cerebellar ataxia type 1 (ARCA-1), also known as autosomal recessive spinocerebellar ataxia type 8 (SCAR8), is caused by spectrin repeat containing nuclear envelope protein 1 (SYNE1) gene mutation." (PMID 35281832, 2022).
bipolar disorder (12 papers, 2011 to 2024). A disorder of the brain that causes unusual shifts in mood, energy, activity levels and the ability to carry out day-to-day tasks. "Genes encoding the cytoskeleton-interacting proteins PLEC and PARVB are risk factors for Alzheimer’s disease, and genetic variants of PLEC and SYNE1 are high-risk alleles for bipolar disorder." (PMID 36400935, 2022). "Genome-wide association studies (GWAS) suggest that rs9371601 in the SYNE1 gene is a risk SNP for bipolar disorder (BPD) in populations of European ancestry, but further replication analyses across distinct populations are needed." (PMID 31236099, 2019). "SYNE1 gene encodes nesprin-1 protein and genome-wide association studies have revealed the strong association of SYNE1 gene with bipolar disorder and major depression." (PMID 32038460, 2019). "Intriguingly, a large-scale genome-wide association analysis of bipolar disorder identified SYNE1 as one of the susceptible loci (Psychiatric GWAS Consortium Bipolar Disorder Working Group, 2011)." (PMID 26035387, 2015). "Previous GWA studies of bipolar disorder have implicated several potential susceptibility genes, such as SYNE1 on chromosome 6q25.2, ODZ4 on 11q14.1, ANK3 on 10q21.2, CACNA1C on 12p13.3, and NCAN on 19p13.1." (PMID 23326512, 2013). "SYNE1 mutations are associated with cerebellar recessive ataxia and bipolar disorder." (PMID 36569910, 2022). "In particular, a recent study showed that genetic variation in the CPG2 region of SYNE1 could be linked to glutamatergic synapse dysfunction and the susceptibility to bipolar disorder." (PMID 32038460, 2019). "Therefore, future research addressing whether mice that are deficient in Sun1 and/or Sun2, or Syne1 and/or Syne2 show cognition phenotypes such as schizophrenia or bipolar disorder could be beneficial in the field of psychiatric medicine." (PMID 26035387, 2015). "Previous studies have also shown evidence that SYNE1 is affected in bipolar disorder." (PMID 33384710, 2020). "Large-scale GWAS have identified Syne1 as a top risk locus for major psychiatric disorders including schizophrenia, bipolar disorder, major depression, ADHD, and autism spectrum disorder, with particularly strong associations with bipolar disorder, second only to ANK3." (PMID 39304885, 2024).
ovarian carcinoma (12 papers, 2010 to 2023). A malignant neoplasm originating from the surface ovarian epithelium. "This study evaluates the SYNE1 mutation frequency, its association with tumor mutation burden, and the downstream effects of SYNE1 mutations in ovarian cancer." (PMID 37762518, 2023). "We observed an increased frequency of SYNE1 mutations in women with ovarian cancer residing in Kentucky when compared to women in other parts of North America." (PMID 37762518, 2023). "This study evaluates the SYNE1 mutation frequency, association with TMB, and downstream effects of SYNE1 mutation in ovarian cancer." (PMID 37762518, 2023). "SYNE1, a less commonly mutated gene, had notable alterations in 10% of gynecologic malignancies and 5% of epithelial ovarian cancers." (PMID 37762518, 2023). "Mutations of SYNE1 have been found in colorectal cancer, glioblastoma, and ovarian cancer, and methylation of the gene was also frequently found in lung adenocarcinoma and colorectal cancer." (PMID 30211214, 2018). "Interestingly, SYNE1 is also directly adjacent to the estrogen receptor, and polymorphisms within SYNE1 have been linked strongly to estrogen mediated events, such as ovarian cancer." (PMID 25315199, 2014). "In our population of 50 ovarian cancer patients treated at the Markey Cancer Center, 16 patients (32%) exhibited the SYNE1 mutant phenotype." (PMID 37762518, 2023). "SYNE1 alterations are found in 10% of gynecologic malignancies and 5% of epithelial ovarian cancers." (PMID 37762518, 2023). "SYNE1 mutation is associated with increased TMB and immune cell infiltration in ovarian cancer and may serve as an additional biomarker for immunotherapy response." (PMID 37762518, 2023). "Taken together, there is evidence that SYNE1 may be a predictive biomarker for immunotherapy response in ovarian cancer." (PMID 37762518, 2023). "Since ovarian cancer is generally considered a “cold” tumor with a low TMB and lack of CD8+ T cells, this provides additional support for the evaluation of SYNE1 as a biomarker of immunotherapy response." (PMID 37762518, 2023). "Among the PPI networks of SYNE1, CDK12, and PGS1, the ovarian and other cancer-related gene SYNE1 is located 19 kb downstream of ESR1, and it partially contributes to ovarian cancer." (PMID 34763659, 2021). "Genomic reports identify the downregulation of SYNE1 in ovarian cancer and other malignancies, but the consequence of this is not well understood." (PMID 37762518, 2023). "In addition, KLF4 was identified as a putative upstream regulator of drug resistance in ovarian cancer and together with ST3GAL5, SYNE1, CXCL8, HERC5, FOSL1, ARRDC4 merits further studies." (PMID 28473707, 2017). "In addition to that, the function of TTN, CSDM3, RYR2, USH2A and SYNE1 has never been established in ovarian cancer." (PMID 32626534, 2020).
endometriosis (11 papers, 2017 to 2025). The growth of functional endometrial tissue in anatomic sites outside the uterine body. "GREB1 and SYNE1 also contain overlapping signals for infertility and endometriosis, but there is strong evidence against shared causal variants (PP >75%)." (PMID 40229599, 2025). "While GREB1 and SYNE1 also contain overlapping signals for infertility and endometriosis, there is strong evidence against shared causal variants (PP>75%, Supp." (PMID 38562841, 2024). "Two well-known endometriosis loci, SYNE1 and CDKN2B-AS113,14, were significantly associated with both the positive control and the EHR-asymptomatic cluster." (PMID 39315247, 2024). "In endometriosis, based on GWAS, meta-analysis, and whole-exome sequencing (WES) analysis on a cohort of 80 endometriosis patients, SYNE1 is identified as a candidate gene in endometriosis." (PMID 38742190, 2024). "Downregulation of SYNE1 may also promote development of endometriosis or PCOS by regulating sex steroid hormone, such as estrogen." (PMID 38742190, 2024). "Five additional new loci significantly associated with the risk of endometriosis (p < 5 × 10−8) of genes involved in sexual steroid hormone pathways (FN1, CCDC170, ESR1, SYNE1 and FSHB) were identified, for a total of 16 genomic regions associated with endometriosis risk in one or more populations." (PMID 32143537, 2020). "In addition to replicating previously reported loci, we identify five novel loci significantly associated with endometriosis risk (P<5 × 10−8), implicating genes involved in sex steroid hormone pathways (FN1, CCDC170, ESR1, SYNE1 and FSHB)." (PMID 28537267, 2017). "We conducted a GWA meta-analysis of ∼7 million SNPs in 17,045 endometriosis cases and 191,596 controls, confirmed 9 out of 11 previously reported European risk loci, and identified five new genomic regions in or near CCDC170, SYNE1, FSHB, FN1 and 7p12.3 harbouring endometriosis risk loci." (PMID 28537267, 2017). "Therefore, we speculate that downregulation of SYNE1 may promote migration and invasion of endometrial cells in endometriosis or PCOS by regulation nuclear malleability and morphology." (PMID 38742190, 2024). "For instance, SYNE1 and GREB1 showed specific associations with the uterine disorders cluster, suggesting that these genes might play distinct roles in the pathogenesis of these phenotypic presentations of endometriosis." (PMID 39315247, 2024). "Only rs12037376 (CDC42/WNT4), rs71575922 (SYNE1/ESR1), and rs77294520 (GREB1) associate with leiomyoma after correction for the number of tests (P < 0.05/19 = 2.6 × 10−3), with all three variants showing the same direction of effect for endometriosis and leiomyoma (logistic regression)." (PMID 30194396, 2018). "In addition to replicating 9 of the 11 previously reported European risk loci, this GWA meta-analysis identified 5 novel loci significantly associated with endometriosis risk (P<5 × 10−8), implicating genes involved in sex steroid hormone pathways (FN1, CCDC170, ESR1, SYNE1 and FSHB)." (PMID 28537267, 2017). "The expression of SYNE1 and DNM3 were significantly decreased in endometrium of both endometriosis and PCOS compared to control subjects." (PMID 38742190, 2024). "The relationship between SYNE1 and PCOS, and the mechanisms of SYNE1 in endometrium of endometriosis or PCOS is currently unclear." (PMID 38742190, 2024). "Microarray and RNA-seq verified the expressions of SYNE1 and DNM3 were significantly altered in the endometrium of patients with endometriosis or PCOS compared to those of control subjects." (PMID 38742190, 2024). "SYNE1 and DNM3 were potential shared genes between endometriosis and PCOS." (PMID 38742190, 2024). "In addition, microarray dataset and RNA sequencing dataset indicated the mRNA expressions of SYNE1 and DNM3 were downregulated in endometrium of patients with endometriosis or PCOS compared with control groups." (PMID 38742190, 2024).
schizophrenia (11 papers, 2011 to 2024). A major psychotic disorder characterized by abnormalities in the perception or expression of reality. "According to a large-scale exome-wide association analysis of schizophrenia, SYNE1 is a high risk gene." (PMID 31712567, 2019). "All four family members were either homozygous or heterozygous for the bipolar risk genotypes in the SYNE1, ANK3, CACNA1C, ODZ4 (TNM4) and ZNF804A genes, of which ZNF804A is also a schizophrenia risk allele." (PMID 32377792, 2020). "Among the genes with two hits uniquely in cases were three candidate genes linked to autism by a literature-curated database, DMD, SYNE1, and TBL1X and two genes implicated in schizophrenia (GRIK4) and intellectual disability (PQBP1)." (PMID 26185613, 2015).
dilated cardiomyopathy (10 papers, 2012 to 2025). Cardiomyopathy which is characterized by dilation and contractile dysfunction of the left and right ventricles. "In Emery–Dreifuss muscular dystrophy and dilated cardiomyopathy patients, mutations in SYNE1 have been found, which affects nuclear morphology and impairs protein-protein interaction with lamin A/C and SUN2." (PMID 33330489, 2020). "SYNE1 aberrances were mainly associated with arthrogryposis and muscular dystrophies (Online Mendelian Inheritance in Men), but more recent papers have identified its involvement in dilated cardiomyopathy." (PMID 40076866, 2025).
cardiomyopathy (9 papers, 2018 to 2023). A disease of the heart muscle or myocardium proper. "Genetic analysis allowed to identify a de novo heterozygous missense mutation in SYNE1 gene (chr6:152665253:G > C), supporting physician to reach a correct diagnosis in patient affected by cardiomyopathy associated with a difficult clinical scenario." (PMID 31110749, 2019). "Additional variants were present in SYNE1 and SCN5A genes related to various cardiac conduction defects (Brugada syndrome, long QT interval type 3, and cardiomyopathy)." (PMID 33829027, 2021). "In the family of our study, the parents carrying with only SYNE1 p.S4607F or LDB3 p.M456R/MYH6 p.S180Y mutations presented with no phenotype of cardiomyopathy or arrhythmia." (PMID 33949037, 2021). "Data analysis also indicated that there are many genes related to cardiomyopathy, such as TTN, NEFH, PLEC, CASQ2, and SYNE1." (PMID 33200202, 2020).
gastric cancer (9 papers, 2016 to 2025). A primary or metastatic malignant neoplasm involving the stomach. "There are also genes, such as SYNE1, the high level of SYNE1 promoter methylation was associated with poorer chemotherapy efficacy in advanced gastric cancer patients." (PMID 36046250, 2022). "In addition, cumulative evidences suggest that changes in SYNE1 expression levels, somatic mutations, promoter methylation level, and single-nucleotide polymorphisms are related to the occurrence and development of lung cancer, oral cancer, hepatocellular carcinoma, and gastric cancer." (PMID 34513706, 2021). "Although SYNE1 was not identified as a driver gene in our ACGEJ samples, it has been identified as a significantly mutated gene in Western patients with ACGEJ and Chinese patients with gastric cancer." (PMID 36439494, 2022).
lung carcinoma (9 papers, 2015 to 2025). "We successfully identified epistasis in RGL1:RAD51B in ALL and NSCLC lung cancer, SYNE1:RNF43 in ADE and FHIT:TSPAN8 in SQC risk development." (PMID 30956756, 2019). "Interestingly, all the three significant epistasis—-RGL1:RAD51B in ALL and NSCLC lung cancer, SYNE1:RNF43 in ADE and FHIT:TSPAN8 in SQC risk development—-were displayed as interaction between networks." (PMID 30956756, 2019). "Several reports have indicated that in various cancers and tumors, including lung cancer, colorectal cancer, and serrated adenomas, SYNE1 expression is epigenetically repressed through hypermethylation of the CpG island, residing in either the promoter or coding region." (PMID 34944636, 2021).
muscular dystrophies (9 papers, 2016 to 2025). "The homozygous SYNE1 early termination mutation produces a severe, congenital muscular dystrophy phenotype, affecting several tissues, probably because expression of KASH+ nesprin-1 is massively reduced." (PMID 27350129, 2016). "Further, there are muscular dystrophies with similar symptoms to FSHD, that are linked with genes of the nuclear envelope: striated muscle laminopathies (e.g. Emery–Dreifuss-muscular-dystrophy and limb-girdle-muscular-dystrophy 1B) are caused by mutations in EMD, LMNA or SYNE1, among others." (PMID 38796645, 2024).
glioblastoma (8 papers, 2014 to 2025). The most malignant astrocytic tumor (WHO grade IV). "As in our study, another analysis of The Cancer Genome Atlas glioblastoma cases revealed an association between increased SYNE1 expression and longer survival." (PMID 38665799, 2024). "Mutations in SYNE1, for example, have been implicated in human glioblastoma progression and survival, and SYNE1 has also been identified as a potential driver gene in cervical cancer development." (PMID 36552829, 2022). "SYNE1 mutation was associated with autosomal recessive cerebellar ataxia and is known to be associated with glioblastoma and lung, ovarian, colorectal, and head and neck cancers." (PMID 29340043, 2017). "Recurrent SYNE1 mutations were first identified in glioblastoma multiforme (GBM) tumors." (PMID 27160712, 2016).
autism (6 papers, 2011 to 2022). Persistent deficits in social interaction and communication and interaction as well as a markedly restricted repertoire of activity and interest as well as repetitive patterns of behavior. "For example, the SYNE1 gene has been implicated in autism by large-scale sequencing studies that have identified several autism-associated de novo variants in this gene." (PMID 36409768, 2022). "Likewise, genetic analysis of a consanguineous family identified a homozygous mutation in SYNE1 that is causative for autism." (PMID 36409768, 2022). "However, this study suggests that the SYNE1 gene is more frequently associated with ADHD than with autism." (PMID 33384710, 2020). "Identifying additional SYNE1 and/or SYNE2 mutations that show associations or direct involvement in autism will aid to elucidate the underpinned molecular mechanisms." (PMID 34573277, 2021).
colorectal cancer (6 papers, 2018 to 2022). A primary or metastatic malignant neoplasm that affects the colon or rectum. "Mutations in SYNE1 are reported to be associated with colorectal cancers in previous studies." (PMID 29871594, 2018). "SYNE1 and forkhead box protein E1 promoter methylation have been identified as candidate biomarkers in colorectal cancer plasma DNA." (PMID 34513706, 2021). "In addition to these commonly mutated genes, genomic mutations in SYNE1, TTN, NEB, and CCDC168 were found to be associated with a poor prognosis of colorectal cancer in this study." (PMID 35975176, 2022).